VSIG4 (V-set and immunoglobulin domain containing 4)
Diseases named in the same sentence as VSIG4 in open-access papers (continued):
Sharing a sentence is not in itself a finding about the gene and the disease.
type 2 diabetes (3 papers, 2021 to 2026). "To determine the role of VSIG4 in type 2 diabetes, we examined VSIG4 expression in a type 2 diabetic animal model and podocyte." (PMID 35888119, 2022). "In conclusion, VSIG4 was upregulated in an animal model of type 2 diabetes and was related to albuminuria and pro-fibrotic markers." (PMID 35888119, 2022). "The results showed that the mRNA and protein expression of VSIG4 were upregulated in an animal model of type 2 diabetes." (PMID 35888119, 2022). "In conclusion, VSIG4 was upregulated in the kidneys, as well as in the urine and serum of an animal model of type 2 diabetes." (PMID 35888119, 2022). "Combined with the previous results, these findings proved that VSIG4 expression is clearly upregulated in an animal model of type 2 diabetes." (PMID 35888119, 2022). "Therefore, the present study was designed to determine the role of VSIG4 in a well-characterized animal model of type 2 diabetes." (PMID 35888119, 2022).
chronic kidney disease (2 papers, 2023 to 2026). Impairment of the renal function secondary to chronic kidney damage persisting for three or more months. "VSIG4 may be involved in pathogenesis and disease progression in chronic kidney disease models." (PMID 36836636, 2023).
colitis (2 papers, 2020 to 2022). Inflammation of the colon. "For example, VSIG4 was found to exacerbate an experimental model of colitis in which NLRP3 inflammasome activation is associated with limiting disease progression." (PMID 32856419, 2020). "Excessive NLRP3 activation, which can be caused by knockdown of V-set and immunoglobulin domain-containing 4 (VSIG4), protects mice from DSS-induced colitis." (PMID 35677444, 2022).
colon cancer (2 papers, 2022 to 2024). "Results of quantitative real-time polymerase chain reaction (qRT-PCR) showed that LGR5 and VSIG4 were differentially expressed between normal and colon cancer samples." (PMID 36186438, 2022). "Expression levels of LGR5, VSIG4, GZMB, and ITLN1 were tested in colon cancer and adjacent normal tissues via qRT-PCR method." (PMID 36186438, 2022). "Notably, relationships between VSIG4, HLA-DRA, and HLA-DRB6 were observed in this study, indicating that VSIG4 may mediate the expression of HLA-DR family genes through antigen presentation and be involved in the immune activation mechanism of MSI colon cancer." (PMID 39726813, 2024).
Hepatic steatosis (2 papers, 2025). Steatosis is a term used to denote lipid accumulation within hepatocytes. "Decreases in the expression of Vsig4 and increases in that of Hnf6, as observed in the liver of OBX mice, are relevant to glucose intolerance and hepatic steatosis." (PMID 41021537, 2025).
Hepatitis (2 papers, 2017 to 2022). Inflammation of the liver. "Interestingly, in an animal model of liver damage, mice with a deletion of VSIG4 would develop severe hepatitis." (PMID 36387195, 2022).
osteosarcoma (2 papers, 2021 to 2023). A usually aggressive malignant bone-forming mesenchymal neoplasm, predominantly affecting adolescents and young adults. "Four gene expression signatures (PLEKHO2, GBP2, MPP1, and VSIG4) linked to osteosarcoma prognosis were identified within the TARGET-osteosarcoma cohort, categorizing patients into two subgroups." (PMID 38169731, 2023). "Although PLEKHO2, VSIG4, MPP1, and GBP2 have been implicated in the pathogenesis of several cancers, their roles in osteosarcoma have not been reported to date." (PMID 38169731, 2023). "Finally, we focused on investigating the role of GBP2 in osteosarcoma and did not extensively explore the functions of PLEKHO2, VSIG4, and MPP1." (PMID 38169731, 2023).
prostate tumor (2 papers, 2024 to 2026). "Here, we identified VSIG4 as a key regulator of prostate tumor-resident macrophage fate through single-cell sequencing analysis." (PMID 41622236, 2026).
renal fibrosis (2 papers, 2023 to 2025). A final common manifestation of a wide variety of chronic kidney diseases characterized by glomerulosclerosis and tubulointerstitial fibrosis. "Compared with the control group, VSIG4 protein in urine and kidney tissue of UUO mice is significantly increased, but whether VSIG4 is involved in renal fibrosis caused by UUO is still unknown." (PMID 41218386, 2025). "We have provided a deeper understanding of VSIG4’s role in the progression of renal fibrosis, particularly through its involvement in immune regulation and fibrosis-associated pathways such as EMT." (PMID 41218386, 2025). "Meanwhile, western blot results showed that VSIG4 expression was increased in UUO-induced renal fibrosis." (PMID 41218386, 2025). "Among them, VSIG4 has been widely reported as a key regulator in fibrosis across various diseases, although its specific mechanism in renal fibrosis remains unclear." (PMID 41218386, 2025). "To investigate the expression of VSIG4 in renal fibrosis, we first constructed a UUO mouse model." (PMID 41218386, 2025). "These classifiers may act in concert with VSIG4, influencing immune responses and contributing to the fibrotic process in renal fibrosis." (PMID 41218386, 2025). "In addition, we plan to address this in future work to better understand the role of VSIG4 in the pathogenesis of renal fibrosis." (PMID 41218386, 2025). "Therefore, we established a mouse model of UUO to explore the involvement of VSIG4 in renal fibrosis." (PMID 41218386, 2025). "Considering that the EMT is one of the main mechanisms of renal fibrosis, VSIG4 may be related to kidney diseases." (PMID 36836636, 2023). "Furthermore, the present study suggests that the other classifiers identified may also contribute to the fibrotic process, potentially acting in concert with VSIG4 to promote renal fibrosis." (PMID 41218386, 2025). "•VSIG4 may be an important mediator involved in renal fibrosis." (PMID 41218386, 2025). "In summary, we identified five key genes (SFN, ARHGAP9, VSIG4, ISG20, CD3G) that can distinguish patients with renal fibrosis from controls, making them potential biomarkers for disease diagnosis and treatment monitoring." (PMID 41218386, 2025). "Therefore, we speculate that VSIG4 is an important mediator in the development of renal fibrosis." (PMID 41218386, 2025). "To investigate the role of VSIG4 in CKDs, in this study, we investigated the expression of VSIG4 in UUO- and doxorubicin-induced kidney injury mouse models, which are known animal models of renal fibrosis." (PMID 36836636, 2023). "VSIG4 is highly expressed in UUO and may be an important mediator involved in renal fibrosis." (PMID 41218386, 2025).
steatosis (2 papers, 2017 to 2021). Increased lipid within the cytoplasm of cells. "Furthermore, Vsig4−/− obese mice tended to develop with high liver triglyceride levels and steatosis, as well as enlarge adipocytes." (PMID 29109438, 2017).
viral infection (2 papers, 2017 to 2025). "Here, we used an influenza virus-infected VSIG4-deficient animal model to define the detailed mechanisms involved in acute virus infection." (PMID 41150440, 2025). "However, the potential role of VSIG4 in controlling acute viral infection, as well as its underlying mechanisms, has yet to be elucidated." (PMID 41150440, 2025). "Understanding the mechanisms by which VSIG4 mediates this acute viral infection and how VSIG4 facilitates respiratory immunity is of growing interest." (PMID 41150440, 2025). "Since VSIG4 molecular influences immune protective function during sublethal dose influenza virus infection, it is worth exploring the mechanism during acute viral infection." (PMID 41150440, 2025). "Our findings build upon this understanding by demonstrating that VSIG4 plays a critical role in maintaining immune homeostasis during acute viral infection." (PMID 41150440, 2025). "Furthermore, Vsig4−/− mice exhibit markedly higher mortality over MHV-3 viral infection, clearly due to the exacerbated macrophage-dependent inflammation in vivo." (PMID 29109438, 2017). "However, the role of VSIG4 in acute viral infections remains largely unclear." (PMID 41150440, 2025). "This suggests that recombinant VSIG4, or agents capable of enhancing its expression, may serve as promising therapeutic strategies for controlling inflammation, particularly during acute viral infections." (PMID 41150440, 2025). "Although Vsig4 deficiency did not seem to affect the basal expression level of these factors before viral infection, qRT-PCR data showed that MHV-3 infection super-induced Vsig4−/− PEMs to express Fgl2, Tnf, Il-1β, and Il-6." (PMID 29109438, 2017).
Acute hepatitis (1 paper, 2020). Acute hepatic injury resulting from inflammation typically accompanied by increased serum alanine transaminase activity. "In addition to Vsig4, Nbs targeting C-type lectin domain family 4 member F (Clec4F) have been used to monitor KC dynamic during liver inflammation by SPECT: 99mTC-labeled anti-Clec4F Nb accumulation is reduced in a ConA-induced acute hepatitis model." (PMID 33353213, 2020).
anaplastic thyroid cancer (1 paper, 2025). "Recently, VSIG4+ tumor-associated macrophages (TAMs) have been identified as a specific subset that infiltrates aggressive cancers, including anaplastic thyroid cancer (ATC)." (PMID 39920772, 2025).
arteriosclerosis (1 paper, 2022). A vascular disorder characterized by thickening and hardening of the walls of the arteries. "VSIG4 activate macrophages, through induction of chemokines, promote the migration of inflammatory cells to the lesion area, and participate in the pathogenesis of arteriosclerosis." (PMID 36061537, 2022).
asthma (1 paper, 2024). "The 15 most significant DEGs included genes known to play a role in wound healing (FN1, CDH11), immune response (VSIG4, HS3ST4), and asthma drug response (PTHHD4, SPTBN1, FKBP5)." (PMID 38806494, 2024).
Atrophy (1 paper, 2020). Any weakening or degeneration, especially through lack of use. "In aged mice, VSIG4‐positive Mφ were found in remnants of the thymic cortex following involution, a process of age‐related thymic atrophy, conversion to adipose tissue, and immunosenescence (Thomas, Wang, & Su, 2020)." (PMID 32856419, 2020).
brain hemorrhage (1 paper, 2023). "VSIG4 also attenuates NLRP3 via the JAK2-STAT3-A20 pathway and ameliorates neuroinflammation after brain hemorrhage in mice." (PMID 37153746, 2023).
breast tumor (1 paper, 2021). "The results indicated that the protein levels of IL-10, CD163, and VSIG4 were significantly increased in breast tumor tissues in mice overexpressing HPSE, indicating that HPSE might promote macrophage M2 polarization (CD163, VSIG4) by upregulating IL-10." (PMID 34461608, 2021).
cardiomyopathies (1 paper, 2023). "The multiple evidence above suggests that VSIG4 is involved in the protection of cardiac function through immunomodulatory effects, and therefore activation of VSIG4 expression in the myocardium may be an important immunotherapy for the treatment of various cardiomyopathies, including DCM." (PMID 37108502, 2023).
emphysema (1 paper, 2022). "For the complement pathway, VSIG4 was upregulated in the control, but not in nicotine-pretreated emphysema samples, and Factor D protein was significantly upregulated in both the control and nicotine emphysema samples." (PMID 35241086, 2022).
endometriosis (1 paper, 2022). The growth of functional endometrial tissue in anatomic sites outside the uterine body. "Other members of the complement activation pathway, such as complement C3a receptor 1 (C3AR1) and V-set and immunoglobulin domain containing 4 (VSIG4), are also known in endometriosis, and upregulation of complement and coagulation pathways in endometriosis has been well-reported in several studies." (PMID 36339397, 2022).
Fulminant hepatitis (1 paper, 2017). Acute hepatitis complicated by acute liver failure with hepatic encephalopathy occurring less than 8 weeks after the onset of jaundice. "In contrast, forced expression of Vsig4 in susceptible mice provides significant protection against MHV-3-induced fulminant hepatitis." (PMID 29109438, 2017). "These combined data suggest that increasing the expression of VSIG4 might have therapeutic potentials for fulminant hepatitis and other macrophage-associated inflammatory disorders." (PMID 29109438, 2017).
head and neck squamous cell carcinoma (1 paper, 2021). A squamous cell carcinoma that arises from any of the following anatomic sites: lip and oral cavity, nasal cavity, paranasal sinuses, pharynx, larynx, and salivary glands. "Importantly, GPX4 expression was positively correlated with the expression levels of monocyte markers (CD14 and CD115) and M2 macrophage markers (VSIG4 and MS4A4A) both in ESCA and in head and neck squamous cell carcinoma (HNSC)." (PMID 34722530, 2021).
Hypoalbuminemia (1 paper, 2025). The concentration of albumin in the blood circulation is below the lower limit of normal. "Multivariate Cox analysis confirmed hypoalbuminemia (HR [95% CI: 2.051-6.408]) and the expression of VSIG4 (HR [95% CI: 1.201-5.067]) as independent risk factors and rituximab use as a protective factor of OS (HR [95% CI: 0.223-0.718])." (PMID 40539047, 2025).
Impaired glucose tolerance (1 paper, 2020). An abnormal resistance to glucose, i.e., a reduction in the ability to maintain glucose levels in the blood stream within normal limits following oral or intravenous administration of glucose. "Expression of VSIG4 was analyzed in gWAT and iWAT from obese, Western‐type high‐fat diet‐fed mice exhibiting increased intraabdominal fat and signs of impaired glucose tolerance." (PMID 32856419, 2020).
influenza (1 paper, 2025). An acute viral infection of the respiratory tract, occurring in isolated cases, in epidemics, or in pandemics; it is caused by serologically different strains of viruses (influenzaviruses) designated A, B, and C, has a 3-day incubation period, and usually lasts for 3 to 10 days. "Meanwhile, we observed elevated expression of pro-inflammatory cytokines and prominent inflammatory foci with varying degrees of lung damage in the VSIG4-deficient mice following influenza infection." (PMID 41150440, 2025). "The recombinant VSIG4 protein slightly improved protection from the influenza challenge, suggesting regulatory functions of VSIG4 during infection." (PMID 41150440, 2025).
invasive breast carcinoma (1 paper, 2020). A carcinoma that infiltrates the breast parenchyma. "Similarly, VSIG4 was previously identified as a marker highly upregulated by invasive breast cancer near tumor‐adjacent adipose tissue compared to a distant site from the same breast." (PMID 32856419, 2020).
kidney injury (1 paper, 2023). Trauma to the kidney. "We found that VSIG4 expression was upregulated and that it correlated with the urinary albumin level in the doxorubicin-induced kidney injury animal model." (PMID 36836636, 2023). "Furthermore, the level of urinary VSIG4 was highly correlated with the level of urinary albumin in the doxorubicin-induced kidney injury mouse model." (PMID 36836636, 2023). "Urinary and intrarenal VSIG4 levels were significantly increased in both UUO and doxorubicin-induced kidney injury mouse models." (PMID 36836636, 2023).
leukemia (1 paper, 2024). A malignant (clonal) hematologic disorder, involving hematopoietic stem cells and characterized by the presence of primitive or atypical myeloid or lymphoid cells in the bone marrow and the blood. "The qRT-PCR results revealed significant differential expression patterns of LGR5 and VSIG4 in normal and human leukemia cell lines (HL-60 and MV-4-11)." (PMID 38322112, 2024).
Lewis lung carcinoma (1 paper, 2020). "VSIG4 may play a direct role in cancer progression, as Vsig4 deficiency was shown to suppress the growth of Lewis lung carcinoma (LLC1) isografts." (PMID 32856419, 2020).
liver fibrosis (1 paper, 2023). "Several studies have reported that VSIG4 expression improves liver fibrosis in hepatic Kupffer cells 27,28." (PMID 37153746, 2023).
lung adenocarcinoma (1 paper, 2020). A carcinoma that arises from the lung and is characterized by the presence of malignant glandular epithelial cells. "Similar observations were found in a xenograft model of A549 lung adenocarcinoma in immunocompromised mice, wherein immunofluorescent staining revealed an abundant population of tissue‐resident Mφ (CD206‐ and/or CD301a‐positive) expressing VSIG4 within the normal stroma on the tumor periphery." (PMID 32856419, 2020).
lupus (1 paper, 2024). "VSIG4’s diagnostic utility in lupus has been rigorously evaluated with a larger cohort in a previous study." (PMID 38534254, 2024).
metastatic tumor (1 paper, 2024). "Recruited MoMs (TIM4−/VSIG4−) and tissue-resident KCs (TIM4+/VSIG4+) expand during metastatic disease progression; however, MoMs are located within metastatic tumor lesions, whereas KCs are mostly found at the periphery." (PMID 38355776, 2024).
myocardial ischemia (1 paper, 2025). A disorder of cardiac function caused by insufficient blood flow to the muscle tissue of the heart. "In myocardial ischemia/reperfusion (I/R) injury, VSIG4 inhibits M1 macrophage polarization by blocking TLR4/NF-κB signaling, thus preventing cardiomyocyte apoptosis." (PMID 40630963, 2025).
nonalcoholic fatty liver disease (1 paper, 2022). "Moreover, VSIG4 has been reported to be markedly down-regulated in fatty livers in patients with nonalcoholic fatty liver disease and in obese mice, whereas the loss of VSIG4 has been shown to accelerate lipid deposition, fibrosis and the severity of inflammatory responses." (PMID 36035989, 2022).
ovarian tumors (1 paper, 2025). "PPI analysis showed that CLIC3 was associated with VSIG4 which is overexpressed in ovarian tumors exhibiting with progression and recurrence of the cancer." (PMID 41465326, 2025).
pancreatic ductal adenocarcinoma (1 paper, 2023). An infiltrating adenocarcinoma that arises from the epithelial cells of the pancreas. "In our study, we aimed to identify the role of a novel immune checkpoint molecule V-set Ig domain-containing 4 (VSIG4) in pancreatic ductal adenocarcinoma (PDAC)." (PMID 37097516, 2023).
Parkinson disease (1 paper, 2025). A progressive degenerative disorder of the central nervous system characterized by loss of dopamine producing neurons in the substantia nigra and the presence of Lewy bodies in the substantia nigra and locus coeruleus. "Further analysis of the signaling pathways involving CD163, FPR1, and VSIG4 revealed that CD163 was enriched in 76 pathways, including ribosome, Parkinson’s disease, leishmania infection, Fc gamma R-mediated phagocytosis, and B cell receptor signaling." (PMID 40630963, 2025).
pneumonia (1 paper, 2025). An acute, acute and chronic, or chronic inflammation focally or diffusely affecting the lung parenchyma, caused by an infection in one or both of the lungs (by bacteria, viruses, fungi, or mycoplasma.). "On day 8, post-inoculation with a sublethal dose of the PR8 virus, the lungs of the VSIG4-deficient mice exhibited severe pneumonia." (PMID 41150440, 2025).
pulmonary fibrosis (1 paper, 2025). Chronic progressive interstitial lung disorder characterized by the replacement of the lung tissue by connective tissue, leading to progressive dyspnea, respiratory failure, or right heart failure. "Additionally, studies on pulmonary fibrosis and cardiac fibrosis suggest that VSIG4 may play a role in regulating immune cells, such as macrophages, which are critical in the fibrotic process." (PMID 41218386, 2025).
renal cell carcinoma (1 paper, 2023). "The results showed that FUCA1 was down-regulated and SLC40A1, VSIG4, CRYBB1 and LIPA were up-regulated in renal cell carcinoma and 786-O, and the difference was statistically significant." (PMID 37361571, 2023).